NUDCD1 (NudC domain containing 1)
Diseases named in the same sentence as NUDCD1 in open-access papers (continued):
Sharing a sentence is not in itself a finding about the gene and the disease.
cancer (continued). "NUDCD1 plays a vital function in the pathogenesis of cancer; however, the molecular mechanisms behind its functions in PC remain a mystery." (PMID 34325402, 2021). "The mRNA of NudCD1 is expressed in heart and testis of normal tissues, and is overexpressed in several cancers." (PMID 29021621, 2017). "Moreover, NUDCD1 overexpression in cancer cell lines promoted VEGF secretion, tumor growth and angiogenesis in vitro and in vivo." (PMID 37338527, 2023). "We then tested the genetic and epigenetic features of NUDCD1 in cancers." (PMID 37338527, 2023). "In addition, we found that NUDCD1 methylation was significantly negatively correlated with its expression in most cancer types." (PMID 37338527, 2023). "Multiple genetic and epigenetic features of NUDCD1 exist in different cancers." (PMID 37338527, 2023). "Mutation of NUDCD1 may influence the DFS and PFS in cancer patients and SNV patients had a longer PFS versus NUDCD1-WT patients in UCEC." (PMID 37338527, 2023). "The CTD was also used to establish an interaction network between NUDCD1-chemicals-cancers." (PMID 37338527, 2023). "We also explored relationships between NUDCD1 methylation and immune infiltrates and identified differences of immune infiltration between mutant and WT NUDCD1 in specific cancers and correlations between NUDCD1 CNV and immune infiltrates." (PMID 37338527, 2023). "Data from GEPIA2 suggested that NUDCD1 expression was correlated with OS in 7 types of cancers." (PMID 37338527, 2023). "NUDCD1 acts as a crucial component of apoptosis and immune responses, has been identified as an oncoprotein that is frequently activated or upregulated in various human cancers, and is known as an important kind of cancer antigen." (PMID 34325402, 2021). "Notably, a network of NUDCD1-chemicals-cancers established in our study may provide an alternative insight in cancer drug screening applications." (PMID 37338527, 2023). "Whether NUDCD1 functions as a biomarker for cancers still requires investigation." (PMID 37338527, 2023). "Lastly, based on the existing literature and analysis in our study, the laboratory verification of NUDCD1 role in STAD was conducted with our clinical samples and cancer cells." (PMID 37338527, 2023). "NudC domain containing 1 (NUDCD1, also known as CML66 or OVA66) is an oncoprotein that is frequently activated or upregulated in various human cancers and well known as an important cancer antigen." (PMID 34325402, 2021). "The tumor immune microenvironment consists of cancer cells, blood vessels and immune infiltrates and this complex milieu provides the functional space for NUDCD1 in a contact or non-contact manner." (PMID 37338527, 2023). "Moreover, NUDCD1 correlated with the CTRP and GDSC drug sensitivity and acted as a link between chemicals and cancers." (PMID 37338527, 2023). "The functions of NUDCD1 in these cancers have been demonstrated via cell and animal-based evidence but a clinical data-based pan-cancer analysis has not been conducted." (PMID 37338527, 2023). "Moreover, Kaplan-Meier Plotter (KM Plotter) was used to draw overall survival curves of cancer patients and the OS from GSCA indicated distinct survival differences between high and low NUDCD1 expression groups in multiple cancers." (PMID 37338527, 2023). "But there is still no pan-cancer analysis available for NUDCD1 in human cancers." (PMID 37338527, 2023).
tumor (8 papers, 2014 to 2025). "The gene encoding NUDCD1 possesses several isoforms derived from 12 alternatively-spliced exons and is overexpressed in numerous human tumor tissues." (PMID 37338527, 2023). "NUDCD1 expression was positively correlated with TMB (tumor mutation burden) in STAD, LUAD and BRCA while negatively correlated with TMB in UVM and THCA." (PMID 37338527, 2023). "In the present study, NUDCD1 was upregulated in PC cell lines and tumor tissues, and its upregulation had a remarkable association with poor prognosis." (PMID 34325402, 2021). "Tissue-based RNA expression can be affected by tumor heterogeneity or individual patient differences so we further analyzed NUDCD1 RNA expression in different cell lines." (PMID 37338527, 2023). "Immunohistochemistry data from HPA indicated that the NUDCD1 protein was more highly expressed in tumor samples compared to normal tissues in BRCA, LUAD and SARC." (PMID 37338527, 2023). "NUDCD1 is also multifunctional and involved in the regulation of cellular biological processes especially in tumor cells." (PMID 37338527, 2023). "The examination of subcutaneous tumorigenesis in nude mice revealed that tumor weight and volume were reduced remarkably following NUDCD1 knockdown." (PMID 34325402, 2021). "Data obtained from in vivo experiments revealed that NUDCD1 knockdown inhibited the tumor growth, proliferation, and metastasis by modulating the EMT and inducing the apoptosis of PC cells." (PMID 34325402, 2021). "Hence, in order to further explore the mechanism whereby NUDCD1 influences tumor progress, we integrated the co-expression network and analysis with the NUDCD1-related gene set." (PMID 37338527, 2023). "Additionally, we analyzed genetic and epigenetic features of NUDCD1 expression and a deeper analysis revealed the role of NUDCD1 in the tumor-immune system and tumor-immune infiltration as an antigen." (PMID 37338527, 2023). "We established a tumor xenograft model ro clarify more clearly the role of NUDCD1 in PC." (PMID 34325402, 2021). "Downregulation of NudCD1 in tumor cells that showed a high expression of the protein resulted in a down-regulation of some oncogenic genes such as CTSL, MMP15, uPAR, VEGF, COX-2, S100A4, MUC1, MDM2 and RAC110 and an increase of the resistance to 5-fluorouracil-induced apoptosis." (PMID 29021621, 2017). "Thus, as a tumor-related antigen, NUDCD1 may play multiple roles in different tumor types and could impact tumor immunity." (PMID 37338527, 2023). "Also, we established a tumor xenograft model to determine the role of NUDCD1 in vivo." (PMID 34325402, 2021). "We found that the mRNA expression of NUDCD1 was significantly higher than that in pericarcinous tissues; moderate and strong staining of NUDCD1 was mainly observed in high-grade STAD tissues, while most of the low-grade tumor tissues showed weak staining." (PMID 37338527, 2023). "Other studies have shown that another NudC family member, the NudC domain-containing 1 (NudCD1), also known as the chronic myelogenous leukaemia tumour antigen 66 (CML66), is overexpressed in a variety of tumour cell lines or tissues." (PMID 36104662, 2022). "The top 100 genes that correlated with NUDCD1 expression indicated 4 common members: FAM91A1, DCAF13, MED30 and DDX21, and their corresponding expression in different tumor types could be established." (PMID 37338527, 2023). "Herein, we found correlations between NUDCD1 expression and MSI and TMB across tumor types." (PMID 37338527, 2023). "In addition, expression of NudCD1 significantly correlated with the degree of tumour differentiation and the TNM staging (P < 0.01), as well as the depth of invasion of the primary tumour and lymph node metastasis (P < 0.05)." (PMID 36104662, 2022).
NUDCD1 also shares sentences with these, for which no sentence is quoted: ovarian carcinoma (5 papers); acute lymphoid leukaemia (1); Bladder urothelial carcinoma (1); breast carcinoma (1); Breast invasive carcinoma (1); cervical squamous cell carcinoma (1); cholangiocarcinoma (1); chondrosarcoma (1); colon adenocarcinoma (1); endocervical adenocarcinoma (1); Esophageal carcinoma (1); giant cell tumor (1); Glioblastoma multiforme (1); hepatocellular carcinoma (1); infection (1); Kidney chromophobe (1); liver cancer (1); lung adenocarcinoma (1); Lung squamous cell carcinoma (1); lymph node metastasis (1); meningioma (1); pancreatic ductal adenocarcinoma (1); rectal cancer (1); rectum adenocarcinoma (1); renal carcinoma (1); Stomach adenocarcinoma (1); thymoma (1); uterine corpus endometrial carcinoma (1).